CRP (C-reactive protein)
Diseases named in the same sentence as CRP in open-access papers (continued):
Sharing a sentence is not in itself a finding about the gene and the disease.
tumor (continued). "Also, the downregulation of CRP and COX-2 further gives credence to the anti-HCC potentials of the C. sativa extract because high serum level of CRP has been reported to signify poor prognosis of patients with HCC, while COX-2 overexpression has been shown to inhibit tumor cell apoptosis." (PMID 37434213, 2023). "In this case, the patient’s serum CRP level significantly reduced from 36 mg/L to 2.69 mg/L since Camrelizumab and RT for L5 metastasis intervention, as well as CN afterwards, which may reflect the combination therapy of ICI and RT does reduce the tumor burden." (PMID 34211459, 2021). "The role of several inflammatory markers such as platelet‐to‐lymphocyte ratio (PLR), CRP, albumin, and NLR have been extensively studied in the context of various malignancies, as these markers might reflect the interaction between the immune system and tumor microenvironment." (PMID 34159754, 2021). "Thus, our findings indicate that CRP concentration evaluation in routine clinical practice may have an advantage as a prognostic biomarker in CRC patients, as this protein most comprehensively reflects the clinicopathological features of the tumor." (PMID 34441316, 2021). "However, CRP does not usually increase during ICI-mediated tumor regression." (PMID 31192215, 2019). "Sometimes, when unexplained increases in CRP and LDH were found in non-infected patients, clinicians often needed to consider whether it was caused by a definite tumour progression, so this study chose the cutoff values at 100% specificity and relatively highest sensitivity as a reference." (PMID 30976022, 2019). "Therefore, elevated CRP from baseline may indicate inflammation by tumor progression or irAE rather than an antitumor immune response from ICI treatment." (PMID 31192215, 2019). "The RDW of these patients who were later diagnosed with tumor was higher than that of non-tumor patients (mean value: 15.1 vs 14.6%, P=0.022), and the other tumor-related indicators were erythrocyte sedimentation rate, CRP, hemoglobin level and serum iron equality." (PMID 31815279, 2019). "Importantly, uni- and subsequent multivariate Cox-regression analysis including markers of liver and kidney function (AST, bilirubin, creatinine), tumor markers (CEA) as well as markers of systemic inflammation (CRP) revealed that the prognostic impact was independent of these parameters." (PMID 30653586, 2019). "Laboratory tests used to identify systemic inflammatory markers such as serum levels of C-reactive protein or albumin may overcome these two problems however, these parameters might be altered in cirrhotic patients with or without tumour disease, therefore their utility is questionable." (PMID 29262546, 2017). "An elevated CRP level may reflect a non-specific inflammatory response to tumor necrosis or local tissue damage, which may be indicative of a favorable environment for the establishment and growth of tumor." (PMID 23618082, 2013). "Although our data showed no positive correlation between serum IL-6 and CRP levels, elevation of the CRP level is primarily determined by an increase of circulating IL-6, and the IL-6 level is correlated with the serum CRP level as well as with tumor histological grade and metastasis." (PMID 19656379, 2009). "While tumor location alone was not an independent predictor of OS or DFS, factors such as CRP, LVI, PNI, and tumor budding emerged as critical determinants of patient outcomes." (PMID 40277783, 2025). "CRP has been identified as an inflammatory marker that is elevated in NSCLC, and its levels correlate with tumor size and grade but not with NSCLC subtypes, indicating a potential indicator of poorer prognosis and survival outcomes." (PMID 41179937, 2025). "The complete blood count, C-reactive protein (CRP), procalcitonin, erythrocyte sedimentation rate (ESR), G test, GM test, and tumor markers including CEA, SCC, CA125, pro-GRP and NSE were normal." (PMID 41140660, 2025).
tumor (continued). "Unlike CRP, which is primarily produced in the liver, PTX3 is synthesized by cells within the tumor microenvironment, offering a more accurate reflection of tumor activity." (PMID 39594709, 2024). "Although tumor markers were not remarkable, inflammatory markers showed elevated levels of ESR (erythrocyte sedimentation rate) of 95 mm/hr and CRP (C-reactive protein) of 83 mg/L, with normal hemoglobin." (PMID 38638740, 2024). "The C-reactive protein (CRP) level was normal (0.15 mg/dL), erythrocyte sedimentation rate (ESR) was very slightly elevated (18 [normal: 0–15] mm/h), and no positive tumor markers were identified." (PMID 36701731, 2023). "Tumor cells are negative for SAA and CRP and show normal (retained) cytoplasmic expression of LFABP." (PMID 37835484, 2023). "The aim of the study was to investigate the association of the detectability of ctDNA at a non-prespecified time point in a patient’s treatment with tumor progression, and to correlate ctDNA with commonly used biomarkers (protein S100, LDH, and CRP)." (PMID 36077695, 2022). "There were significant differences among the three groups in the following items: WBC, neutrophil, albumin, ALT, CRP, PNI, CAR, ALBI, CEA, CA19-9, type of hepatectomy, lymph node status, maximum tumor size, major vascular invasion, and AJCC staging." (PMID 36358877, 2022). "The prognostic significance of the CRP/albumin ratio existed in Stages III and IV PC patients and had no connection with the primary tumor location." (PMID 35965580, 2022). "They found that CRP level was not an independent predictor of PFS and tumor recurrence on multivariate analysis." (PMID 35847918, 2022). "Downregulation of other tumor markers, including CEA and CA19-9 levels was not significantly different between the CRP and CUP groups." (PMID 33727662, 2021). "These subgroups were characterized by low CRP and CA19-9 levels irrespective of disease stage and tumor differentiation." (PMID 33437015, 2021). "A retrospective study proposed that the inflammatory markers PLR and CRP (but not NLR) have prognostic value, possibly because they reflect the value of parameters representative of tumor growth and aggressiveness." (PMID 34535132, 2021). "The negative correlation between tumor stromal infiltration by FOXP3+ lymphocytes and SIR defined as elevated plasma CRP, as described in the present study, is congruent with that observation." (PMID 32316975, 2020). "This study indicated that CRP was the best predictor of OS in unresectable HCC patients treated with lenvatinib, and this finding was independent of Child-Pugh score and existing tumor factors." (PMID 33351844, 2020). "Intriguingly, levels of serum AAT do not correlate with levels of C-reactive protein, neutrophils-to-leukocyte ratio, and do not correlate with SERPINA1 expression or AAT staining in the tumor tissue." (PMID 31487965, 2019). "In this case, high accumulation of 18F-FDG was observed in the tumor without increased WBC count and CRP value." (PMID 31338615, 2019). "While NLR and CRP were significant predictive factors for detection of tumor recurrence, the combination of NLR with CRP or with other systemic biomarkers had no additive effect." (PMID 29774108, 2018). "The main diagnostic characteristic of IHCA, namely activation of the JAK-STAT-pathway, can be immunohistochemically proven by a homogenous, non-mosaic-like expression of C-reactive protein (CRP) and Serum amyloid A (SAA) in all tumor cells." (PMID 26404250, 2015). "We also have shown that CRP is an independent marker of poor prognosis in patients with HCC, irrespective of tumor stage and liver function." (PMID 23374755, 2013). "There have been not yet clear explanation how elevated CRP and NLR would be responsible for tumor progression." (PMID 23409924, 2013). "Laboratory findings are nonspecific; abnormality often observed in elevation of CRP and ESR and/or increase of WBC count, reflecting the inflammatory characteristics of the tumor." (PMID 23091756, 2012).
tumor (continued). "Although IL-6 and CRP levels were not correlated with other pathological findings, VEGF level was significantly correlated with tumor size (p = 0.012) and CEA (p = 0.038)." (PMID 20465852, 2010). "Furthermore, because C-reactive protein concentration is independent of tumour stage and grade, the presence or absence of a systemic inflammatory response, might, form the basis of a new prognostic score that reflects not only the tumour but also the host response." (PMID 15726119, 2005). "The transient elevation in white cell count and CRP seen immediately after HIFU are not clinically significant, and likely reflect a systemic inflammatory response to the tumour ablation." (PMID 16189519, 2005). "However, CRP and NLR are inherently non-specific, which often limits their ability to accurately reflect tumor-related inflammation status." (PMID 41346687, 2025). "Landmark survival analysis has been commonly applied before to investigate non-baseline predictors, e.g., tumor dynamics, and avoids predicting events before the monitoring time of the predictor (i.e., prediction of PFS or OS before assessment of CRP at treatment cycle 3)." (PMID 38001689, 2023). "H&E staining of tumor tissues also showed that CRP-MC (Trip) and CRE-NP (α-M) pretreated tumor cells had the most obvious apoptosis and necrosis, whereas the CRP-MC (Trip) group had no cytotoxic effect on central tumor cells." (PMID 36869341, 2023). "Furthermore, lower OS was also associated with a PS ≥ 2 (HR 2.42, p = 0.019), absence of primary tumor resection (HR 2.21, p = 0.0008), decreased albumin level (HR 1.98, p = 0.001), and elevated LDH (HR 2.07, p = 0.002) and CRP (HR 2.39, p < 0.0001) levels." (PMID 37400504, 2023). "However, other clinical parameters, including age, sex, tumour location, tumour size, clinical stage, tumour subtype, ALP, the ESR, CRP and the PLR, presented no relevance to pCR in our study." (PMID 34983443, 2022). "In addition to positive correlations of L3SMI and L3PMI with height, body weight, and BMI, strong negative correlations with the tumor marker CA19-9, the inflammatory marker CRP, and the leukocyte count were particularly striking." (PMID 34771524, 2021). "We think that CRP value suggests HCC status, independent of existing tumor stage and tumor marker." (PMID 33351844, 2020). "Based on these studies, the levels of pre-EBV-DNA, pre-HGB, pre-ALB, pre-CRP, and pre-LDH have been evaluated in this study, combined with gender, age, T stage, N stage, smoking, drinking history, family history of tumor, and radiotherapy with/without IC or CC." (PMID 33363024, 2020). "Age (P=0.2636), gender (P=0.5930), size of the tumor (P=0.1769), ECOG PS (P=0.0778), RCC subtype (P=0.6203), the presence of grade 3 component (P=0.4325), the presence of MVI (P=0.1114) and CRP (P=0.0515) were not significantly different between the two groups." (PMID 25435945, 2015). "To ensure that our results were driven by the tumor itself and not by inflammatory events, we analyzed the correlations between the MFI of HVEM on monocytes and their subsets and inflammatory markers, including leucocyte count, C-reactive protein (CRP), and bilirubin." (PMID 40243455, 2025). "In such cases, before concluding that a tumor is an IHCA, it is important to be sure that CRP immunopositivity is stronger in the tumor than in nontumorous liver, and to also perform SAA staining for comparison; otherwise, the staining may not be interpretable." (PMID 35954333, 2022). "Using the following prognostic factors, the MMPS could distinguish patients with different prognosis in terms of OS: tumor volume pre-chemotherapy (pre-CTX) > 500 ml, CRP pre-CTX > 30 mg/l, non-epithelioid histology in pre-CTX biopsy, and progressive disease according to modified RECIST criteria." (PMID 32661672, 2020).
tumor (continued). "Age, high ASA-PSC, right-sided tumours, pT3d-, pN1a-, and pN2b-subclassification, increased LNR, high-grade malignancy, vascular and perineural invasion, no adjuvant treatment, pre- and postoperative CEA, and CRP correlated with increased hazard of mortality in unadjusted analyses." (PMID 31893351, 2020). "When we considered correlations between the clinicopathological features of the tumor and serum levels of the tested proteins in relation to the histological type of OC, we found a positive correlation only between serum CXCL-8 levels and CRP concentrations (p = 0.021) (data not shown)." (PMID 30820705, 2019).
bacterial infection (1,247 papers, 2005 to 2026). "The results suggest that CRP and blood cortisol levels can effectively predict bacterial infection with equivalent diagnostic efficacy." (PMID 39946377, 2025). "Their findings demonstrated that BChE serves as a reliable predictor for septic shock caused by bacterial infections, outperforming traditional inflammatory markers such as CRP and PCT." (PMID 40861055, 2025). "It has been reported that the diagnostic accuracy of PCT markers is higher than CRP markers in patients hospitalized with suspected bacterial infection." (PMID 41315982, 2025). "CRP is produced during inflammation in the human body, and high levels of CRP are associated with bacterial infections, even in children." (PMID 39932324, 2025). "Severely elevated CRP levels (>50 mg/dL) are associated with bacterial infections in approximately 90% of cases." (PMID 40642736, 2025). "In this retrospective study, we identified age, neurological complications, multidrug-resistant bacterial infection, CSF neutrophils (CSF N), and CRP as independent risk factors for 30-day mortality in affected patients." (PMID 41357526, 2025). "For viral respiratory infections, SAA combined with routine blood parameters serves as an effective preliminary screening tool, whereas CRP demonstrates higher diagnostic value for bacterial infections." (PMID 41308272, 2025). "This biological mechanism explains why CRP levels can rise dramatically, often 100-fold or more, during acute bacterial infections, including melioidosis caused by B. pseudomallei." (PMID 41010302, 2025). "While increased CRP can be associated with lupus arthritis or serositis, high CRP usually is an indication of bacterial infection in SLE patients." (PMID 40632603, 2025). "Diagnostic value of cortisol, CRP and their combined Logit P diagnostic model for bacterial infection." (PMID 39946377, 2025). "On the other hand, the combined use of MPS and azithromycin can simultaneously target inflammation and potential bacterial infections, thereby alleviating the inflammatory response caused by pathogens and reducing serum CRP and PCT levels." (PMID 40821637, 2025). "CRP levels, at low concentrations (1–5 μg/mL), are indicative of cardiovascular risk, while elevated levels (>10 μg/mL) can distinguish between bacterial infections (>20 μg/mL) and viral infections (<20 μg/mL)." (PMID 40277527, 2025). "Treatment was promptly initiated with intravenous cefotaxime sulbactam sodium (150 mg/kg/day for 10 days) to address the underlying bacterial infection, supported by elevated C-reactive protein (CRP, 148.24 mg/L) and chest CT findings of lung consolidation." (PMID 41041448, 2025). "In the logistic regression model, CRP levels were significantly associated with serious bacterial infections (SBIs) (OR 1.014, 95% CI: 1.004–1.024, p = 0.007), indicating that higher CRP values correlate with an increased risk of SBI." (PMID 41065831, 2025). "We conducted ROC curve analysis to evaluate the diagnostic efficacy of CRP and blood cortisol levels in distinguishing between bacterial and non-bacterial infections during the early stages of DKA." (PMID 39946377, 2025). "For C-reactive protein, its increased level during bacterial infections is a risk factor for MDR DFI." (PMID 39165660, 2024). "Patients receiving tocilizumab are at a high risk of developing serious bacterial infections, and the diagnosis is often delayed because symptoms such as fever and elevated C-reactive protein levels are often minimal." (PMID 38962614, 2024). "The diagnostic effect of LMR and WBC × CRP was deemed good or excellent in patients with influenza B, healthy people, and patients with a bacterial infection." (PMID 38306568, 2024). "Based on the ROC curves, this study found that WBC and CRP had a high diagnostic power in influenza B and bacterial infection; however, the corresponding cutoff values were still within the normal reference range (WBC: 6.75 × 109/L, CRP: 8.5mg/L)." (PMID 38306568, 2024).